BNIP3 (BCL2 interacting protein 3)
Diseases named in the same sentence as BNIP3 in open-access papers (continued):
Sharing a sentence is not in itself a finding about the gene and the disease.
tumor (continued). "In this investigation, we determined three pyroptosis-related genes including CAPN1, BNIP3, and CASP6 as prognostic signatures of NSCLC based on the expression profile with 146 pyroptosis-related genes from the TCGA database, which are overexpressed in the tumor tissues." (PMID 36092153, 2022). "We thus propose a simple model in which the LMP1-induced BNIP3 through ERK/HIF1α are crucial to the disruption of an interaction between Bcl-2 and Beclin1, thereby releasing the negative autophagic blockade, and further triggering the radioresistance of the NPC tumor." (PMID 33795637, 2021). "In addition, hypoxia promotes PDGFR-induced autophagy in tumor cells dependent on HIF-1α signaling while independent of BNIP3 and BNIP3L." (PMID 28729825, 2017). "Thus, similar to Parkin, BNIP3 and NIX both appear to play tumor suppressor roles." (PMID 25810907, 2015). "The earlier findings that under hypoxic conditions expression of BNIP3 can be induced by the transcription factor HIF-1α prompted us to evaluate the extent to which expression of BNIP3 in haematopoietic tumour cell lines could be induced by hypoxia." (PMID 15756280, 2005). "However, it is worth noting that BNIP3 is not highly expressed in all tumours." (PMID 36200262, 2022). "However, BNIP3 silencing in tumour cells does not impact on hypoxia-driven poorer prognosis." (PMID 18728663, 2008). "This is further demonstrated in RCC tumor tissue where BNIP3 and VHL expression levels are lower compared to adjacent non-tumor tissues, whereas the expression of HIF-1α was higher in the same tumor tissues." (PMID 33573362, 2021). "The present study demonstrated that in C26 tumor bearers the mitophagy marker PINK1 increased, whereas the other mitophagy-related protein BNIP3 was not significantly affected, although it showed an increasing trend." (PMID 30823492, 2019). "The expression of Glut-1, CAIX, BNIP3, MCT4, LC3A, LC3B and p62 was observed not only in tumor cells but also in stromal cells, which has not been thoroughly described in previous studies." (PMID 24020991, 2013). "Although tumours with both methylated BNIP3 and stromal HIF-2α expression showed a poorer patient survival when compared with HIF-2α-negative tumours, this was not related to apoptosis (data not shown)." (PMID 18728663, 2008). "In the absence of BNIP3, breast cancer cells are unable to eliminate dysfunctional mitochondria, which results in increased mitochondrial ROS and the upregulation of HIF-1α, a key transcription factor in tumor formation." (PMID 38067169, 2023). "However, sorafenib resistance in HCCLM3-SR cells (low endogenous expression of BNIP3/BNIP3L) was not reversed by MenSCs, suggesting that the crosstalk between MSCs and tumour cells is also affected by intertumour heterogeneity." (PMID 37005657, 2023). "That both VEGF and BNIP3, but not HIF-1α, protein levels were inversely correlated to the tumor ascorbate content agrees with the observation that FIH may be more dependent on ascorbate for activity than the PHDs." (PMID 24551593, 2014). "Although in HIF-2α stromal-negative CRCs, BNIP3 methylation occurred in 61% (33 out of 54) and did not influence prognosis, in the HIF-2α-positive tumours, methylation was observed at almost equal frequency, 52% (68 out of 132), but was associated with poorer patient survival (P=0.006)." (PMID 18728663, 2008). "Furthermore, we did not detect differences in apoptotic levels between tumours with or without CA9 expression, regardless of the BNIP3 methylation status." (PMID 18728663, 2008).
cancer (189 papers, 2005 to 2026). A tumor composed of atypical neoplastic, often pleomorphic cells that invade other tissues. "Increased BNIP3 levels in cancer patients have been linked to good as well as poor prognosis, as BNIP3 contributes to both pro-cell death and pro-survival signals." (PMID 40113750, 2025). "The association of BNIP3 with Kaplan–Meier survival analysis was performed on both the publicly available cancer clinical database and the TCGA datasets." (PMID 39945227, 2025). "This study aimed to define the potential of mitigating mitophagy via BNIP3 downregulation in preserving mitochondrial integrity, counteracting skeletal muscle loss in experimental cancer cachexia." (PMID 39766033, 2024). "Hypoxia-inducible factor 1-alpha (HIF1A), which is activated by the growth of cancer cells, causes hypoxia and upregulates BNIP3." (PMID 38262996, 2024). "It is reported that ceramide-induced the upregulation of BNIP3 in glioma cells, which further activates mitophagy and causes cancer cell death." (PMID 38262996, 2024). "Abnormal methylation of several apoptosis-related genes, such as DAPK and Bcl-2 interacting protein 3 (BNIP3), has been reported in various cancers, and BNIP3 methylation is associated with poor prognosis in GC." (PMID 37771430, 2023). "BNIP3 silencing by DNA methylation is a common event in many types of cancers, and a clinical investigation suggested that the methylation frequency in the BNIP3 and BNIP3L promoters is associated with a poor prognosis for patients with HCC." (PMID 37005657, 2023). "Another study analyzed 81 patients with unresectable CRC treated with 5-FU-based regimens and demonstrated that the loss of BNIP3 expression in cancer cells increased resistance to 5-FU-based drugs and worsened prognosis." (PMID 37784019, 2023). "Our study unraveled BNIP3 upregulation as a hallmark characterizing cancer cell subpopulation with increased fitness and proliferation." (PMID 35912211, 2022). "In malignant gliomas, ceramide can upregulate BNIP3 expression to induce mitophagy and cause cancer cell death." (PMID 36200262, 2022). "Another key transcription factor, NRF2, underlying BNIP3 upregulated cancer cell subpopulation has also recently been indirectly targeted with a chemical proteomic approach." (PMID 35912211, 2022). "Expression of the mitophagy receptor BNIP3 declines in several types of cancer and is associated with cancer metastasis and chemoresistance." (PMID 33438778, 2021). "The association of BNIP3 with EMT-related proteins allows it to affect cancer cell dissemination and metastasis." (PMID 33207677, 2020). "Another member of the Bcl-2 family implicated in cancer cell migration, invasion and metastasis is Bnip3, which is considered to be a pro-apoptotic Bcl-2 protein." (PMID 31921862, 2019). "It has also been shown, however, that mitophagy disfunction due to loss of BNIP3 can promote cancer progression." (PMID 31447323, 2019). "BNIP3 upregulation was reported to sensitize cancer cells to apoptosis, while the loss of BNIP3 rendered cancer cell more resistant towards therapy." (PMID 31382612, 2019). "It would be interesting in the future to re-examine the role of BNIP3 in cancer models susceptible to immunosurveillance and ICD." (PMID 29707136, 2018). "Specific defects in mitophagy have been linked to human cancers through deletion of key regulators such as Parkin and BNIP3." (PMID 25810907, 2015). "BNIP3 is an atypical BH3-only family member that has been implicated in the pathogenesis of cancer and heart disease." (PMID 25383959, 2014).
cancer (continued). "Because the apoptotic rates were so low, we also considered potential regulators of alternative death pathways, such as BNIP3, which has been implicated in cancer cell autophagy." (PMID 20652061, 2010). "Additionally, PTBP2 promotes autophagy by binding and stabilizing Bnip3, which has been implicated in cancer cell subpopulations and can be a potential therapeutic target." (PMID 40113750, 2025). "These genes have been revealed to be associated with cancer development in previous studies, and in particular BNIP3, a mitochondrial pro-apoptotic protein in the Bcl-2 superfamily, has been shown to mediate hypoxia-associated autophagy and thus enhance cancer metastasis." (PMID 40438322, 2025). "Correspondingly, transcriptional repression of BNIP3 is associated with several cancer types." (PMID 38177312, 2024). "This study explored whether selectively silencing BNIP3, a mitophagy-related protein upregulated in the muscle of both mouse and human cancer hosts, could help in preventing muscle loss." (PMID 39766033, 2024). "High expression of BNIP3 was associated with deeper scleral invasion and lower cancer survival." (PMID 34568319, 2021). "A small number of hypoxia-associated genes (APLN, HIF1A, and BNIP3), cancer stem cell (CSC) markers (CD24 and CD44), hormonal regulation (HR) genes (ESR1, PGR, and TFF1), other selected genes (PPARGC1A, ILK), and HKGs (RPL32, GUSB, TBP, OAZ1 and NONO) were also included in the panel." (PMID 34206049, 2021). "It was reported initially that slight upregulation in BNIP3 can activate a protective form of autophagy in cancer cells." (PMID 39921807, 2025). "Dysregulation of mitophagy regulators, such as PINK1, Parkin, BNIP3, NIX, and FUNDC1, have been implicated in cancer progression." (PMID 41306556, 2025). "Upregulation of BNIP3 characterizes cancer cell subpopulations with increased fitness and proliferation." (PMID 40113750, 2025). "Many studies have correlated the upregulation of BNIP3/‐L with aggressive malignant behaviour in various types of cancer, such as prostate, colorectal, breast, and endometrial." (PMID 39945227, 2025). "BNIP3, a key mitophagy-related protein, is significantly increased in the muscles of both mice and human cancer hosts." (PMID 39766033, 2024). "Conversely, high BNIP3 levels in certain cancer types or specific cancer cell populations have been associated with adverse patient outcomes." (PMID 39596452, 2024). "Herein, we describe a new model system to enrich sub-populations of cancer cells with high basal levels of mitophagy, based on the functional transcriptional activity of BNIP3 and BNIP3L." (PMID 38834039, 2024). "In cancer, it inhibits the growth of cancer cells by inducing the expression of Foxo3 and inhibiting telomerase reverse transcriptase mRNA to activate mitochondrial-related proteins BNIP3 and BNIP3L." (PMID 38474452, 2024). "In another study, IGF1 (insulin like growth factor 1) signaling activates mitochondrial biogenesis and mitophagy via BNIP3 expression to sustain cancer cell growth and viability." (PMID 38447939, 2024). "In several cancers, including liver, colorectal, pancreatic, and hematopoietic tumors, BNIP3 methylation has been observed." (PMID 39728572, 2024). "Bcl2 and Bcl-XL inhibit the loss of mitochondrial membrane potential mediated by Granzyme B, Bcl-XL, and BNIP3, as well as caspase-mediated apoptosis, thereby promoting cancer cell survival." (PMID 39518013, 2024). "Recent studies showed a significant BNIP3 mRNA increase in experimental models of cancer-induced muscle wasting, reflecting mitophagy induction." (PMID 39766033, 2024). "In cancer, mitochondrial autophagy experiences impairment, affecting mitochondrial autophagy receptors and adapters, including PINK1, Parkin, BNIP3, BNIP3L/NIX, and p62/SQSTM1, along with associated signaling pathways." (PMID 38505747, 2024).
cancer (continued). "Briefly, we employed a BNIP3(L)-promoter-eGFP-reporter system to isolate cancer cells with high BNIP3/BNIP3L transcriptional activity by flow cytometry (FACS)." (PMID 38834039, 2024). "Previous studies have shown that the activation of ATM in cancer cells induces autophagy through the phosphorylation of BNIP3 (Interacting protein 3)." (PMID 39000057, 2024). "Pan-cancer analysis performed in the GEPIA database showed that BNIP3 was lowly expressed in tumors such as CHOL and COAD and highly expressed in tumors such as KIRC and TGCT." (PMID 37190333, 2023). "While PARKIN is best described in the context of mitochondrial damage induced mitophagy, BNIP3’s role in mitophagy is best described in the context of cancer, hypoxia and in liver during fasting." (PMID 37165006, 2023). "BNIP3 silencing tends to occur when cancer cells acquire chemoresistance to drugs, and epigenetic silencing of BNIP3 was also previously observed in sorafenib-resistant cells." (PMID 37005657, 2023). "To confirm this, we focused on autophagy cargo receptors TAX1BP1 and BNIP3 because they have known proapoptotic effects in cancer cells." (PMID 36795483, 2023). "It was shown that the cancer-promoting effects of BNIP3 were reduced by the inhibition of LINC00461 and the overexpression of miR-411-5p." (PMID 35783530, 2022). "PINK1-dependent or BNIP3/NIX-mediated mitophagy has been reported to promote chemoresistance in CSCs of various cancers." (PMID 35725817, 2022). "These in vivo studies provided contradictory evidence on the regulatory effects of BNIP3 in different cancer types, likely due to the co-participation of this mitophagy receptor in other signaling pathways." (PMID 35459212, 2022). "Our results demonstrated that BNIP3 upregulation characterizes cancer cell subpopulations with increased fitness and proliferation." (PMID 35912211, 2022). "Bcl-2 interacting protein 3 (BNIP3), a pro-apoptotic protein, is modulated by hypoxia-inducible factor 1, which has been aberrantly expressed in various cancers." (PMID 35200106, 2022). "As a hypoxia-responsive protein, BNIP3 is often found to be highly expressed in cancers under hypoxic conditions." (PMID 35200106, 2022). "Nevertheless, many other cancer types presented a correlation between their aggressive phenotype and high BNIP3 expression." (PMID 35459212, 2022). "As a result, BNIP3 has been suggested as an important mediator of apoptosis induction following the EGCG‐induced suppression of the DNL pathway in cancer cells." (PMID 35243817, 2022). "We identified a cancer cell subpopulation characterized by upregulated BNIP3 in most epithelial malignancies." (PMID 35912211, 2022). "It has been shown that HCQ, as an autophagy inhibitor, can suppress the activity of BNIP3 and Beclin-1 in mesenchymal cancer cells, leading to significantly reduced spheroid formation." (PMID 35821262, 2022). "BNIP3-positive cancer cells have an upregulated activity in reactive oxygen species pathway, oxidative phosphorylation, as well as MYC targets." (PMID 35912211, 2022). "The differentially expressed genes between BNIP3-positive and BNIP3-negative cancer cells were shown." (PMID 35912211, 2022). "We also interrogated the pathway alterations in cancer cells with upregulated BNIP3 expression with a quantitative pathway enrichment approach using gene set variation analysis (GSVA)." (PMID 35912211, 2022). "Silencing LINC00461 and overexpression of miR-411-5p both inhibited the expression of BNIP3 and blocked the antiapoptotic and cancer-promoting effects of BNIP3." (PMID 35783530, 2022). "Single-cell transcriptomic datasets were used to determine the heterogeneous BNIP3 expression in cancer cells." (PMID 35912211, 2022). "BNIP3 has been shown to be involved in many diseases such as hepatic, cardiovascular diseases, and cancer." (PMID 33681190, 2021).
cancer (continued). "Increased expression of BNIP3 was correlated with increased drug sensitivity of cancer cells to Cisplatin, Carboplatin and Gemcitabine, whereas it was negatively correlated with drug sensitivity of cancer cells to Sunitinib, Palbociclib, and Trametinib." (PMID 34745224, 2021). "BNIP3-mediated mitophagy is involved in multiple physiological and pathological processes, such as limiting the glycolytic shift in radioresistant cancer, promoting the differentiation of cardiac progenitor cells and rescuing renal cells from ischemic injury." (PMID 33879840, 2021). "BNIP3-dependent autophagy influences cell death sensitivity and resistance; therefore, targeting this type of death is a promising approach in cancer therapy." (PMID 33207677, 2020). "We conclude that IGF-1 signals couple the induction of mitochondrial biogenesis with basal levels of mitochondrial turnover through Nrf2 and BNIP3, thus maintaining mitochondrial homeostasis and facilitating cancer progression." (PMID 31936236, 2020). "In this study, we established that IGF-1 mediates a conserved signal through Nrf2 for the induction of BNIP3 expression in cancer cells and MEFs." (PMID 31936236, 2020). "In several human cancer types, including hematological malignancies, lung, breast, gastric, pancreatic, and liver cancer, the epigenetic silencing of BNIP3 expression is reported to correlate with invasiveness and metastasis." (PMID 32274386, 2020). "Here, we delineated the signaling pathway for IGF-1-mediated BNIP3 induction in cancer cell lines and mouse embryonic fibroblasts MEFs." (PMID 31936236, 2020). "BNIP3 action is tissue-specific: it is differently expressed in normal cells and in different cancer types." (PMID 33207677, 2020). "IGF-1-mediated induction of BNIP3 expression was observed in all cancer cell lines tested, including MCF-7 cells." (PMID 31936236, 2020). "PINK1 resulted to be altered in several cancers such as ovarian cancer, glioblastoma, and neuroblastoma and the same came from BNIP3 screening." (PMID 31210843, 2019). "It has been observed in mammalian cancer cells, especially in hypoxic microenvironment, that BNIP3 expression is repressed by promoter aberrant hypermethylation." (PMID 30223788, 2018). "This specific epigenetic alteration allows cancer cells to escape to BNIP3 and BNIP3L proapoptotic activity." (PMID 30223788, 2018). "Inclusion of BNiP3 as arming component of oncolytic measles virus came with the purpose to induce the ablated apoptosis machinery of cancer cells." (PMID 30697531, 2018). "Taken together, these results provide a novel insight into the cross-linking between AhR and autophagy, we addressed the mechanistic BNIP3 modulation by endogenous AhR, which affect cancer cell EMT progression." (PMID 28195146, 2017). "Depending on the cellular context, expression of Bnip3 either induces or delays cell death, and overexpression of Bnip3 has been reported in several types of cancer." (PMID 29084770, 2017). "The expression of BNIP3 can be upregulated under hypoxia in cell lines such as carcinomas, fibroblasts, and macrophages." (PMID 29230415, 2017).